NRXN1 (neurexin 1)
Diseases named in the same sentence as NRXN1 in open-access papers (continued):
Sharing a sentence is not in itself a finding about the gene and the disease.
schizophrenia (continued). "All these indicate that NRXN1 might be a strong candidate gene for schizophrenia." (PMID 21477380, 2011). "Therefore, we used this approach to investigate 11 single nucleotide polymorphisms (SNPs) of the NRXN1 gene lying within regions overlapped by numerous deletions implicated in ASD and schizophrenia, and their effects on brain morphometry in healthy individuals." (PMID 21687627, 2011). "Nevertheless, association of this variant with thalamic volumes is consistent with overlapping neural vulnerability for ASD and schizophrenia as well, and suggests that the NRXN1 gene may influence thalamocortical circuitry that is vulnerable in both disorders." (PMID 21687627, 2011). "NRXN1 and NRXN3 expression was reduced in schizophrenia cortical neurons, and the NRXN3 reduction was the most robust and consistent between the different lines." (PMID 37507766, 2023). "The functional impact of heterozygous deletion of NRXN1 has been investigated in human-derived isogenic embryonic stem cells (ESC) and iPSCs from individuals with schizophrenia and autism." (PMID 37441676, 2023). "The expression of a presynaptic cell adhesion molecule, NRXN1, is disrupted in ASD, schizophrenia and intellectual disability." (PMID 35634471, 2022). "NRXN1 deletion is among the commonest rare genetic factors shared by ASD, schizophrenia, intellectual disability, epilepsy, and developmental delay." (PMID 31893021, 2019). "Several large rare CNVs, including deletions at 2p16.3 overlapping NRXN1, 15q13.3 (BP4-BP5) deletions, and 16p11.2 deletions/duplications, have been identified in schizophrenia and DD/ID." (PMID 29187259, 2017). "These included schizophrenia candidate genes (GRIA1, RIMS1, DLGAP2, GRIN2A, and NRXN1) and several interaction partners." (PMID 25484875, 2014). "The identification of novel rare CNVs in autism (NRXN1, SHANK3, and CNTNAP2) and schizophrenia has generated much excitement." (PMID 21209939, 2010). "Western blots showed significant reduction in NRXN3β protein levels in schizophrenia cortical neurons, but the NRXN1 protein levels were not significantly different between the schizophrenia and healthy control groups." (PMID 37507766, 2023). "Notably, NRXN1 deletions are shared by ASD, schizophrenia, intellectual disability, ADHD, and epilepsy." (PMID 31893021, 2019). "One of the candidate genes in schizophrenia is transcription factor 4 (TCF4), which is positioned on chromosome 18 and is a transcription factor that plays a role in the transcription of Neurexin 1(NRXN1) gene, which is one of the candidate genes for developing schizophrenia." (PMID 32071599, 2019). "Childhood-onset schizophrenia abnormalities identified by Addington and Rapoport include 22q11, 45,X atypical/mosaic, 47,XXX, duplications of 16p11.2, MYT1L duplication on chromosome 2, and NRXN1 deletion on chromosome 2." (PMID 22214315, 2012). "Substantial evidence implicates deletions in the NRXN1 gene in ASD and schizophrenia." (PMID 21687627, 2011). "Therefore, the reduced NRXN1 expression in the MSCs cluster might suggest potential alterations in the regulation of synapse functioning by non-neuronal cells in schizophrenia." (PMID 36192459, 2022).
autism (94 papers, 2008 to 2026). Persistent deficits in social interaction and communication and interaction as well as a markedly restricted repertoire of activity and interest as well as repetitive patterns of behavior. "Deletion of NRXN1 was found to have strong association with autism, mental retardation, and language delay." (PMID 39202440, 2024). "Further studies are needed to clarify the relationship between specific NRXN1 variants and the spectrum of autism symptoms." (PMID 38610832, 2024). "Nevertheless, the NRXN1 gene is associated with neurodevelopmental disorders, including autism, and the detected deletion is most likely pathogenic." (PMID 38539661, 2024). "In cultured neurons, L1 siRNA reduces the expression levels of the long autism genes neurexin-1 (Nrxn1) and neuroligin-1 (Nlgn1) and of the mitochondrially encoded gene NADH:ubiquinone oxidoreductase core subunit 2 (ND2)." (PMID 36768419, 2023). "A number of these down-regulated long genes are associated with autism, including Nrxn1 and Nlgn1, which contribute to the regulation of synaptic functions." (PMID 36768419, 2023). "As possible targets we chose long genes which are associated with autism, namely Nrxn1, Nlgn1, contactin-associated protein 2 (Cntnap2) and discs large MAGUK scaffold protein 2 (Dlg2)." (PMID 36768419, 2023). "Phelan-McDermid Syndrome (PMS, also known as 22q13 deletion syndrome) and NRXN1 deletions (NRXN1ds) are two synaptopathies associated with autism and related neurodevelopmental disorders (NDDs)." (PMID 35250452, 2022). "2p16.3 deletion, involving NEUREXIN1 (NRXN1) heterozygous deletion, substantially increases the risk of developing autism and other neurodevelopmental disorders." (PMID 35142069, 2022). "Recent studies have shown that disease-related genes are highly expressed during early differentiation period, for example, Nrxn1 is enriched in subplate neurons and it is an autism-associated gene." (PMID 33760820, 2021). "Research suggests that NRXN1 is associated with neurodevelopmental disorders characterized by abnormalities in synaptic transmission, such as autism and intellectual disability." (PMID 34357104, 2021). "Hub genes of the turquoise module included one GABA receptor encoding genes such as Gabrb1, one glutamate receptor gene (Grid2) and genes tightly associated with synaptic development and autism (Nrxn1, Lrfn5, Plcb1, Erc2, Frmpd4, Tanc2, Ctnnd2, Dmd)." (PMID 34021132, 2021). "ASD is generally considered a neurodevelopmental disorder; postnatal developmental disorder can also cause autism in patients, and the postnatal mutation of Nrxn1 in neurons leads to autism-like behavior in mice." (PMID 32819434, 2020). "Mutations in the NRXN1 gene have been implicated in a variety of conditions including autism, schizophrenia, and nicotine dependence." (PMID 31316548, 2019). "NRXN1 was implicated as an autism susceptibility gene, though changes in this gene alone are not always detrimental." (PMID 27184741, 2016). "An overlapping NRXN1 CNV was shown in our previous work to have an odds ratio of 14.96, consistent with other publications suggesting a role for NRXN1 variants in autism, as well as other neurological disorders." (PMID 24467814, 2014). "Recently, several lines of studies have shown that mutations in the synaptic adhesion molecules Neurexin 1 and Neuroligins 3 and 4 are associated with autism." (PMID 22615862, 2012). "A number of studies have demonstrated that mutations in the synaptic adhesion molecules neurexin 1 and neuroligins 3 and 4 are associated with autism." (PMID 21595886, 2011). "Prior studies have functionally linked other molecules that are associated with NRXN1 to a range of neuropsychiatric disorders including autism." (PMID 20468056, 2010). "Our finding that NRXN1 is also associated with autism and developmental disorders adds further evidence to the importance of this molecular family to the development of neurodevelopmental disorders." (PMID 20468056, 2010).
autism (continued). "For example, using Affymetrix 10 K SNP arrays, the Autism Genome Project Consortium identified deletions in the neurexin 1 gene (NRXN1) in 2p16 as a cause for ASD, now described in further studies." (PMID 18925931, 2008). "They confirmed the contribution of NRXN1 to autism susceptibility." (PMID 39202440, 2024). "How NRXN1 deletions, which can occur at various positions across the gene, contribute to behaviors associated with autism remains unknown." (PMID 36848371, 2023). "Moreover, the effects of genomic position of a CNV deletion across the NRXN1 locus on isoform expression and subsequent autism-associated behavioral phenotypes remain to be assessed." (PMID 36848371, 2023). "Rare mutations of NRXN1 are strongly associated with Tourette syndrome and autism." (PMID 35052406, 2021). "The genes involved in both neural development and cell–cell adhesion are 6 protocadherins (part of the cadherin family), the autism susceptibility gene NRXN1 (neurexin), and NPTN (neuroplastin), which has been associated with cortical thickness and intellectual ability in humans." (PMID 31628250, 2019). "Our analysis supports the role of several genes/loci associated with autism (e.g., NRXN1, ADNP, 22q11 deletion) and identified new truncating (e.g., GRIK2, ROBO1, NINL, and IMMP2L) or recessive deleterious variants (e.g., KIRREL3 and CNTNAP2) affecting autism-associated genes." (PMID 30675382, 2019). "Furthermore, copy number variations (CNVs) in NRXN1 gene have also previously been implicated in autism, mental retardation and nicotine dependence." (PMID 21477380, 2011). "However, the extent to which specific variants, differing in their positions across the NRXN1 locus, contribute to behavioral traits associated with autism remains unknown." (PMID 36848371, 2023). "Interestingly, mutations in the NRXN1 gene have been associated with autism and other brain disorders, which indicates that neurexin dysfunction could underlie the molecular basis of some mental diseases." (PMID 21559374, 2011). "In a study of whole exon sequencing of 343 ASD families, NRXN1 was revealed as the only one candidate gene for autism." (PMID 39202440, 2024). "Many genes are associated with autism spectrum disorders, and copy number variations and rare gene mutations (e.g., SHANK3, NRXN1, CHD8, SCN2A) are closely linked to autism." (PMID 39734494, 2024). "NRXN1 gene expression appears to be markedly over-expressed in the cohort with autism compared with the control cohort." (PMID 39061976, 2024). "A better knowledge about the multifaceted role of NRXN1 in ASD can provide crucial insights into the neurobiological foundations of autism and pave the way for novel therapeutic strategies." (PMID 38610832, 2024). "Numerous studies support a strong genetic component in the development of autism, with links to mutations involving specific genes such as SHANK3, NLGN3, and NRXN1." (PMID 38435203, 2024). "For example, gene mutations that occur in synaptic proteins, neurexin 1 (NRXN1) and SHANK3 have been associated with the development of autism in early childhood." (PMID 36383254, 2023). "Behaviourally, Nrxn1 and Shank3 animal models display autism-related behaviours that are consistent with observations in clinical studies." (PMID 37441676, 2023).
autism (continued). "Further the NRXN-NLGN-SHANK pathway has been associated with E/I balance, and NRXN1 and SHANK3 deletions have both been implicated in autism." (PMID 37441676, 2023). "Given the large number of CNVs occurring near the 5’-end of NRXN1 locus in humans with autism and that nearly all of those CNVs are heterozygous, we have included this mouse model, particularly the heterozygotes (ΔExon1/+), in our allelic series as well." (PMID 36848371, 2023). "They reported increased autism and hyperactivity features, and poorer social functioning traits in children with NRXN1 deletions compared to neurotypical children." (PMID 37441676, 2023). "Although autism is prevalent in people with NRXN1 deletions, related features such as sensory processing or sensory sensitivities have not yet been examined in-depth." (PMID 37441676, 2023). "Reduction of L1 levels by siRNA downregulated the expression levels of the long autism genes Nrxn1 and Nlgn1 and of the mitochondrial gene ND2." (PMID 36768419, 2023). "Exonic and intronic deletions have been described in clinical cohorts with NRXN1 deletions with the former reported to have an elevated likelihood for neurodevelopmental conditions, autism and intellectual disability." (PMID 37441676, 2023). "This study was designed to investigate the effect of three CNV deletions that vary in location across the NRXN1 locus on behavior phenotypes relevant to autism in both male and female mouse models." (PMID 36848371, 2023). "Here we investigated mouse models carrying different deletions across the Nrxn1 gene, mimicking three distinct ASD-associated deletions observed in humans, and assessed autism-related mouse behaviors." (PMID 36848371, 2023). "In the context of the present study, we would like to mention that L1-70 interacts with topoisomerase 1 and disruption of this interaction leads to changes in expression of the long autism genes neurexin 1 (Nrxn1) and neuroligin 1 (Nlgn1)." (PMID 37238646, 2023). "A 380 kb deletion of NRXN1 occurred in a woman with Asperger’s syndrome, anxiety, and depression as well as in four of her children diagnosed with autism, anxiety disorders, developmental delay, and speech delay." (PMID 34357104, 2021). "Within the autism cluster, the participants with NRXN1 deletions (109NXM and 092NXF) were grouped on the same branch." (PMID 32826066, 2021). "Neurexin performs distinct regulatory functions in different classes of neurons, and any mutation or deletion of Neurexin (NRXN1 and NRXN2) genes have been associated with autism-associated behavioral changes in experimental mice." (PMID 34833061, 2021). "Nrxn1 DNA methylation changes have been correlated with social autistic trait scores in human autism cohorts, demonstrating an example of a gene that is both genetically and epigenetically implicated in ASD6." (PMID 32994467, 2020). "In the P21 rat’s brain of the formalin group, the expression of autism-related gene neurexin 1 (NRXN1), fragile X mental retardation 1 (FMR1), and oxytocin was significantly downregulated, consistent with the gene alteration in ASD." (PMID 27184741, 2016). "As exemplified by CNTNAP2 and NRXN1 gene, heterozygous missense variants confer susceptibility to autism while compound heterozygous mutations of CNTNAP2 and NRXN1 cause Pitts-Hopkins like syndrome." (PMID 27271878, 2016). "Three additional subjects with NRXN1 deletions and autism were identified through the Homozygosity Mapping Collaborative for Autism, and this deletion segregated with the phenotype." (PMID 20468056, 2010). "Taken together, NRXN1 is regarded as one of the strong candidate genes for autism." (PMID 39202440, 2024).
autism (continued). "Comorbid biomarkers may blur diagnostic boundaries, whereas autism-specific biomarkers—such as mutations in SHANK3, NRXN1, and CHD8—are directly tied to autism, but may also be found in other conditions like intellectual disabilities and ADHD." (PMID 39734494, 2024). "Multiple therapeutic strategies have been proposed and tested in animal models, which might lead to translational implications for autism, NRXN1 deletion and/or PMD." (PMID 37441676, 2023). "Given that anxiety is a comorbid condition in a subset of individuals on the autism spectrum, we explored whether the Nrxn1 mutant mice display alterations in anxiety-related behaviors in the elevated zero maze and spontaneous activity in the open field test." (PMID 36848371, 2023). "The cell adhesion molecules NRXN1 and CNTNAP4 are involved in mirror neuron activity and empathic behavior, and RELN has been reported to functionally interact with oxytocin and both neuropeptides have been implicated in autism pathophysiology." (PMID 32966280, 2020). "Importantly, animal models based on genes that have been strongly associated with ASD, such as SHANK3 and Neurexin-1 (NRXN1), further support the idea that autism is a disorder of defective synapses." (PMID 29713304, 2018). "In addition, a small cluster of the network showed co-expression of several genes (NRXN1, CACNA1A, CDH10, and others) associated with autism and/or epilepsy." (PMID 27358653, 2016). "Varying in size and location across the NRXN1 locus, these non-recurrent CNVs are associated with a variety of psychiatric and neurodevelopmental phenotypes, such as developmental delay, intellectual disability, schizophrenia, and autism." (PMID 36848371, 2023). "In a case of a 7-year-old boy with autism, deletions of the NRXN promoter and exons 1–5 were identified, the first evidence linking neuropsychiatric disorders to NRXN1 deletions." (PMID 36737720, 2023). "Thus, Cntn6 may also link to the Nrxn1-Nlgn1 pathway of autism through interaction with Lphn1." (PMID 28018171, 2016). "Some of the genes, such as NCAN and EPHA7, have similar functionality as NRXN1 in mediating neuronal cell interactions, while some other genes, such as PCDH19, CNTN3, CTNNA3, LMX1B, are known autism candidate genes." (PMID 23536886, 2013). "Regarding genetic biomarkers diagnosis, autism-related genes such as SHANK3, NRXN1, and CNTNAP2 exhibit significant complexity and variability, with mutations appearing as single nucleotide polymorphisms (SNPs), small insertions or deletions (Indels), and copy number variations (CNVs)." (PMID 39734494, 2024). "Our findings support the importance of sex, genetic structure, and the amount of functional NRXN1 product in eliciting ASD-relevant behaviors, and the need for animal models carrying anomalies at multiple genes to elucidate the genetic underpinnings of autism." (PMID 36848371, 2023). "Two missense changes seen in the residues of the leader sequence of a-NRXN1 and epidermal growth factor (EGF)-like domain suggests these changes in NRXN1 might be a contributing factor in developing autism." (PMID 31744938, 2019). "Disruption of the NRXN1 gene in autism reported that in autistic individuals, the amino acid alterations in the NRXN1 gene are not frequently present as compared to non-autistic individuals in an NRXN1 gene coding sequence scan." (PMID 31744938, 2019). "Interestingly, other autism candidate genes, including NLGN3, NRXN1, RELN, and GABAA, were also included in the predicted gene network, thus supporting the investigation of our selected genes as ASD-relevant transcriptional targets of RORA." (PMID 23697635, 2013). "For instance, we noted that a strong candidate gene for autism, NRXN1, did not survive the first filtering procedure and was not used for functional annotation analyses." (PMID 20885821, 2010).
autism (continued). "Additionally, circadian activity is markedly altered in mice lacking functional Nrxn1 product, consistent with sleep disturbance being the most common comorbidity in autism." (PMID 36848371, 2023). "Hence, the present study was designed to compare two synaptic gene conditions with high penetrance for autism; Phelan-McDermid Syndrome (PMS, also known as 22q13 deletion syndrome, typically including haploinsufficiency of the SHANK3 gene) and NRXN1 deletions (NRXN1ds)." (PMID 35250452, 2022). "Recently, the Autism Mouse Connectome (AMC) study compared connectivity alterations in 16 autism-related genetic and etiological models including Cntnap2 and Shank3 knockout models, but not Nrxn1." (PMID 35052369, 2021).